CD34 (CD34 molecule)
Diseases named in the same sentence as CD34 in open-access papers (continued):
Sharing a sentence is not in itself a finding about the gene and the disease.
esophageal cancer (1 paper, 2020). A primary or metastatic malignant neoplasm involving the esophagus. "Our study showed a significant association between high CD34 expression in tumoral tissue and a poorer prognosis in patients affected by esophageal cancer (HR 2.10; 95%CI 1.41-3.14; I2 56%; p=0.0003)." (PMID 32368307, 2020). "Two studies 41, 43 were excluded from the meta-analysis of CD34 and the sub-analysis showed a significant association between high CD34 expression in tumoral tissue and a poorer prognosis in patients affected by esophageal cancer (HR 2.02; 95%CI 1.22-3.33; I2 65%; p=0.006)." (PMID 32368307, 2020). "Despite these limitations, we provided a comprehensive analysis of the association between CD34, CD133, Nucleostemin, OCT-4, NANOG and CD90 stemness markers and OS of patients affected by esophageal cancer." (PMID 32368307, 2020). "We found that high expression of CD34, CD133 and Nucleostemin in tumor tissue was associated to a poor prognosis in patients affected by esophageal cancer." (PMID 32368307, 2020). "In summary, our meta-analysis revealed that high expression of CD34, CD133, and Nucleostemin was significantly associated with poor OS, suggesting that these stemness markers are promising prognostic factors in patients affected by esophageal cancer." (PMID 32368307, 2020). "It is therefore conceivable that the percentage of cells expressing CD34 may represent a powerful tool to also assess prognosis in esophageal cancer patients." (PMID 32368307, 2020).
female infertility (1 paper, 2024). Diminished or absent ability of a female to achieve conception. "For example, the EBAG9 locus associated with female infertility is under directional selection, perhaps because EBAG9, which is highly expressed in CD34-/CD41+/CD42+ megakaryocytes, plays a role in T-cell mediated cytotoxicity as part of the adaptive immune memory response to infection." (PMID 38562841, 2024).
Fibrous Meningioma (1 paper, 2020). A WHO grade I meningioma characterized by the presence of spindle cells that form bundles in a collagen matrix. "Besides, compared with SFT, a fibrous meningioma is usually better stained by an EMA antibody, but only mildly or focally positive on CD34 and Bcl-2 staining." (PMID 33327290, 2020).
focal epilepsy (1 paper, 2023). A seizure caused by a localized disorder. "In-utero electroporation of BRAFV600E into the developing mouse brain cause CD34-immunoreactive GG and focal epilepsy." (PMID 36973520, 2023).
gastric leiomyosarcoma (1 paper, 2025). An aggressive malignant smooth muscle neoplasm, arising from the stomach. "The combination of spindle cell morphology, α-SMA and h-caldesmon positivity, CD117 and DOG1 negativity, and high mitotic activity is consistent with the typical profile of gastric leiomyosarcomas and allows differentiation from GISTs, which usually express CD117, DOG1, and frequently CD34." (PMID 41209937, 2025).
gastrointestinal carcinomas (1 paper, 2019). "Furthermore, CD34 expression, which has not been reported in gastrointestinal carcinomas, was positive, which might suggest true dedifferentiation since it has been reported that CD34 is a general marker of progenitor cells." (PMID 30649642, 2019).
giant cell tumor (1 paper, 2021). A benign, intermediate, or malignant tumor that arises from the bone or soft tissue. "Because myeloid cells are components of giant cell tumor histology, we also used T-MVs to stimulate human hematopoietic progenitor cells (CD34+) isolated from healthy donors (see “Material and methods”)." (PMID 34404763, 2021).
gingivitis (1 paper, 2022). A disorder involving inflammation of the gums; may affect surrounding and supporting structures of the teeth. "Antibodies to the CD34 molecule are widely used for immunohistochemical staining of gingival microvessels MVD found in the early stages of gingivitis and may be considered the first step of a complex process with damages countable depending on the gingival index." (PMID 35628885, 2022).
glomerulonephritis (1 paper, 2012). A renal disorder characterized by damage in the glomeruli. "Overexpression of CD34 reflects the pathogenesis of glomerular alterations (e.g. glomerulonephritis) related to age, diabetes, and the severity of the disease." (PMID 22761655, 2012). "Immunohistochemical co-staining of CD34 and α-SMA has been used to study various glomerulonephritis (GN) as a transformed mesangial cell marker." (PMID 22761655, 2012).
Graves disease (1 paper, 2022). Graves' disease is an autoimmune disorder that leads to overactivity of the thyroid gland (hyperthyroidism).It is caused by an abnormal immune system response that causes the thyroid gland to produce too much thyroid hormones. "Of note, a previous study identified stromal cells coexpressing CD34 and thyrotropin receptor in thyroid tissue from donors with Graves’ disease, Hashimoto's thyroiditis, as well as in normal‐appearing thyroid tissue." (PMID 35307951, 2022).
H1N1 influenza (1 paper, 2020). "CD34-expressing ECs respond robustly to H1N1 influenza injury." (PMID 32091393, 2020).
haemophilia (1 paper, 2013). "Although FVIII is absent from platelets under normal conditions, this approach proved successful for storing viable BDDFVIII in platelet progeny derived from tissue-cultured human CD34+G-PBC12 and lentiviral vector-transduced bone marrow transplanted into haemophilia A mice." (PMID 24253479, 2013).
Heat Stroke (1 paper, 2018). A condition caused by the failure of body to dissipate heat in an excessively hot environment or during PHYSICAL EXERTION in a hot environment. "Systemic administration of CD34+ cells derived from human umbilical cord blood (HUCB) was shown to reduce heat stroke-induced mortality in rats." (PMID 29416747, 2018). "Treating rats with CD34+ cells derived from human umbilical cord blood before or after heat stroke has been shown to promote survival." (PMID 29416747, 2018). "We demonstrated that CD34− PDMSCs have anti-inflammatory effects similar to those of HUCB-derived CD34+ cells in rats following heat stroke." (PMID 29416747, 2018). "They found that systemic administration of CD34+ cells derived from HUCB also promoted survival in heat stroke rats by suppressing the inflammatory response." (PMID 29416747, 2018). "We investigated whether CD34– human placenta-derived stem cells (PDMSCs) could improve survival following heat stroke in rats." (PMID 29416747, 2018). "Both CD34− PDMSCs and CD34+ HUCB equally attenuated heat stroke-induced overexpression of both IL-1β and TNF-α in rats." (PMID 29416747, 2018). "Putting together, PDMSCs may promote survival in heat stroke by a protective cell population without the presence of CD34+ cells." (PMID 29416747, 2018).
hemophagocytic lymphohistiocytosis (1 paper, 2020). "The 4-month-old child with a vascular structure positive for LYVE-1, D2-40, CD31, and CD34 died of hemophagocytic lymphohistiocytosis, which was not present in the orbital tissues." (PMID 32516408, 2020).
Hemophagocytosis (1 paper, 2010). Phagocytosis by macrophages of erythrocytes, leukocytes, platelets, and their precursors in bone marrow and other tissues. "An erythropoiesis signature in active sJIA is associated with the expansion of CD34+ cells, also is seen in some patients with FHLH and infection, and may be an indicator of ineffective erythropoiesis and hemophagocytosis due to hypercytokinemia." (PMID 20576155, 2010).
hemosiderosis (1 paper, 2023). Accumulation of iron in internal organs. "The CD34+SC/TC and EC connections with pre-existing blood vessels could facilitate the extravasation of red blood cells with hemosiderosis (abnormal neovessels connecting to blood vessels)." (PMID 36835203, 2023).
Hepatic steatosis (1 paper, 2025). Steatosis is a term used to denote lipid accumulation within hepatocytes. "When encountering nodules with multiple hepatic steatosis, if glypican-3 and heat shock protein 70 are negative, and CD34 does not show diffuse hepatic sinusoidal capillarization, this is an opportune moment to carefully evaluate the expression patterns of GS and CD34." (PMID 41366899, 2025).
hepatitis B (1 paper, 2018). "Patients with other genotypes should be examined further for possible correlation of CD34+ cells with hepatitis B viral load." (PMID 29461203, 2018).
hepatitis C (1 paper, 2015). "There was one case with an autoimmune disorder presenting expression of CD34 in maturing granulocytes without any other abnormality, and one with hepatitis C at diagnosis presenting expression of CD7 in maturing granulocytes." (PMID 25924846, 2015).
Hepatomegaly (1 paper, 2025). Abnormally increased size of the liver. "Our results revealed that significantly higher PDL1 expression on CD34+/CD38- LSCs but not on blasts was associated with hepatomegaly (P = 0.028)." (PMID 40940644, 2025).
herpes simplex infection (1 paper, 2024). "It is because of its association with non-replicative herpes simplex infection, which further shows its association with viral DNA fragmentation that is present inside the infected CD34+ cells." (PMID 39036174, 2024).
herpes zoster (1 paper, 2019). A common dermal and neurologic disorder caused by reactivation of the varicella-zoster virus that has remained dormant within dorsal root ganglia, often for decades, after the patient's initial exposure to the virus in the form of varicella (chickenpox). "Herpes zoster was significantly more common in the CD34-selected group." (PMID 30670057, 2019).
hypercortisolism (1 paper, 2022). "Moreover, we observed a more than 50% upregulation of GR alpha in the PB-derived CD34+ progenitor cells from patients with endogenous hypercortisolism compared to healthy subjects (p < 0.01)." (PMID 36555435, 2022). "Next, we determined whether genes with cell death/survival functions are expressed and are differentially modulated by GCs in PB-derived CD34+-enriched HSPCs from patients with chronic hypercortisolism due to endogenous CS." (PMID 36555435, 2022).
hyperhomocysteinemia (1 paper, 2016). A serious metabolic condition caused by mutations in the MTHFR gene, medications, or nutritional deficiency. "The scatter plots suggested a significant reduction of circulating EPCs (CD34+/CD31+) amount in peripheral blood of hyperhomocysteinemia rats compared with control." (PMID 27391949, 2016).
hyperthyroidism (1 paper, 2021). Overactivity of the thyroid gland resulting in overproduction of thyroid hormone and increased metabolic rate. "We found CD34 and MBL2 were associated with hyperthyroidism." (PMID 34409035, 2021).
inflammatory bowel disease (1 paper, 2023). A spectrum of small and large bowel inflammatory diseases of unknown etiology. "Since CD34 is also involved in the recruitment of various immune cells in the inflammatory site during IBD, these results demonstrated that CD34 played a migration role in the process of immune cells reaching the site of inflammatory bowel disease." (PMID 37051017, 2023).
Inguinal hernia (1 paper, 2020). Protrusion of the contents of the abdominal cavity through the inguinal canal. "Another gene of this family, CD34, was downregulated in humans affected by inguinal hernias." (PMID 32379844, 2020).
keratoconus (1 paper, 2017). A degenerative, structural disorder of the eye, characterized by a cone-shaped protrusion of the cornea. "In particular, in keratoconus TC were unevenly distributed throughout the corneal stroma, with a loss of CD34 immunoreactivity mostly evident in the anterior stroma." (PMID 28714595, 2017). "Indeed, while in control corneas CD34+/PDGFRα+ TC were typically found in the whole corneal stroma, in keratoconus a patchy loss of CD34/PDGFRα immunoreactivity was observed mainly in the subepithelial part of the stroma." (PMID 28714595, 2017).
Krukenberg tumour (1 paper, 2020). "We observed an important increase in adipose resident TCs/CD34+SCs in signet ring cell carcinoma with Krukenberg tumour and peritoneal dissemination (original observation)." (PMID 33353193, 2020). "An intriguing fact that may be of interest in the behaviour of certain neoplasms is the presence of carcinomatous cells surrounded by TCs/CD34+SCs (e.g., in signet ring carcinoma with Krukenberg tumour and peritoneal dissemination)." (PMID 33353193, 2020).
large cell carcinoma (1 paper, 2020). A malignant epithelial neoplasm composed of large, atypical cells. "Furthermore, CD34+ CAFs occurred more often in pulmonary adenocarcinoma (ADC) than in squamous‐cell carcinoma (SCC) or large cell carcinoma (LCC) of the lung (P = 0.006)." (PMID 31760702, 2020).
laryngeal carcinoma (1 paper, 2019). Carcinoma that arises from the laryngeal epithelium. "They suggested that MVD CD34 has an important role in promoting metastases in laryngeal cancer and can serve as a prognostic marker." (PMID 30840126, 2019).
leiomyomatosis (1 paper, 2021). A condition characterized by the presence of numerous small benign smooth muscle neoplasms located throughout the body. "In the report, the immunostaining of the leiomyomatosis-like LAM lesion showed positivity for desmin, caldesmon, HMB-45, and CD117, and showed negativity for CD34." (PMID 34918628, 2021). "Similar to our findings, the smooth muscle cells stained positive for HMB45 and negative for CD34 and CD 117, which suggested leiomyomatosis-like LAM." (PMID 34918628, 2021).
leprosy (1 paper, 2023). Leprosy is a chronic infectious disease affecting primarily the skin and peripheral nervous system. "The results showed that leprosy patients had a low count of mesenchymal cells and a high amount of CD34/CD45 positive cells." (PMID 36595533, 2023).
leptospirosis (1 paper, 2013). A contagious bacterial infection caused by spirochetes of the genus Leptospira. "Its more preserved expression is notable, when compared to CD34 in the microvasculature of the edematous and/or hemorrhagic lung areas in human leptospirosis." (PMID 23951234, 2013). "In leptospirosis, the edematous and/or hemorrhagic areas showed dilated capillaries of the microvascular vasculature and extensive, but nevertheless focal areas with a partial or total lack of CD34 expression." (PMID 23951234, 2013).
Lewis Lung carcinoma (1 paper, 2011). "Further, podocalyxin and CD34 both localize to the site of vascular lumen initiation in Lewis Lung carcinoma tumor-associated vasculature." (PMID 21494591, 2011).
lipid metabolism disorders (1 paper, 2024). "The study reveals that lipid metabolism disorders significantly contribute to cardiac fibrosis by promoting the transformation of CD34+ cells into FABP4+ fibroblasts, worsening heart fibrosis." (PMID 39198543, 2024).
lymphangitis (1 paper, 2014). Inflammation of the lymphatic vessels. "Differential diagnosis with sclerosing lymphangitis is made by staining of the endothelium with monoclonal antibodies to CD31 and CD34." (PMID 25780580, 2014).
Lymphatic Metastasis (1 paper, 2025). Transfer of a neoplasm from its primary site to lymph nodes or to distant parts of the body by way of the lymphatic system. "Definitive identification of the metastatic route requires additional immunohistochemical analysis: lymphatic metastasis is typically associated with D2-40 (podoplanin) positivity, whereas hematogenous metastasis shows CD34 positivity." (PMID 41584594, 2025).
medullary thyroid carcinoma (1 paper, 2017). "Pilot staining of 50 samples with variable PSMA expression including FA (n = 5), FTC (n = 10), PTC (n = 25), PDTC (n = 4), ATC (n = 3), and medullary thyroid carcinoma (MTC; n = 3) with CD31/CD34 and further matching, demonstrated that PSMA was not ubiquitously expressed in tumor microvasculature." (PMID 28701709, 2017).
melanocytic neoplasm (1 paper, 2021). "The proteins encoded by CD34 and CALD1 have been shown to be expressed in various types of STS in dogs, but not melanocytic neoplasms." (PMID 34422947, 2021).
mesenchymoma (1 paper, 2017). A term describing a soft tissue tumor which consists of two or more mesenchymal lines of differentiation, excluding a fibroblastic line of differentiation. "Mesenchymomas are positive for CD117, CD34 and DOG-1 at a high level." (PMID 28492717, 2017).
Miscarriage (1 paper, 2023). A pregnancy that ends at a stage in which the fetus is incapable of surviving on its own, defined as the spontaneous loss of a fetus before the 22th week of pregnancy. "The number of CD34+ vessels per field in placental villi was decreased in the miscarriage group than in the ETP group." (PMID 37968664, 2023). "CD34+ vessel number and vascular endothelial growth factor (VEGF) protein abundance were decreased in miscarriage." (PMID 37968664, 2023).
monocytopenia (1 paper, 2020). "Together with the clinical observation that monocytopenia patient skin has normal MAC numbers and almost no proliferative CD68+cells, yet many CD34+cells, our ex vivo-data further support that human dermal CD68+trMACs arise from an expanding pool of CD34+MAC progenitors after SP stimulation." (PMID 31971954, 2020).
motor neuron diseases (1 paper, 2019). "Understanding the mechanism of controlling CD34+ precursors in ALS may have translational relevance in motor neuron diseases." (PMID 31395804, 2019).
mucinosis (1 paper, 2021). "Likewise, we highlight the association of CD34+SCs/TCs with degenerative fibers in the basophilic degeneration of collagen, and the presence of spindle-shaped, stellate and bulky vacuolated CD34+ stromal cells in cutaneous myxoid cysts, as an example of local mucinosis." (PMID 34298962, 2021).
mucinous tumours (1 paper, 1998). "CD31 and CD34 immunostaining also revealed increased microvessel density in early-stage mucinous tumours (234.6 +/- 28.2; 87.8 +/- 9.2) compared with that observed in both early- (72.8 +/- 15; 12.9 +/- 2.4) and late- (115.6 +/- 26.5; 29.8 +/- 8.5) stage serous tumours (P < 0.001)." (PMID 9649134, 1998).
mucoepidermoid carcinoma (1 paper, 2013). A carcinoma morphologically characterized the presence of cuboidal mucous cells, goblet-like mucous cells, squamoid cells, cystic changes, and a fibrotic stromal formation. "In addition, numerous CD34-positive small vessels were present adjacent to αSMA-positive CAFs in mucoepidermoid carcinoma." (PMID 23588777, 2013).
Multiple Organ Failure (1 paper, 2014). A progressive condition usually characterized by combined failure of several organs such as the lungs, liver, kidney, along with some clotting mechanisms, usually postinjury or postoperative. "In our study, the number of circulating CD34+cells did not correlate with any of the clinical outcome parameters, such as the injury severity score, survival, development of multiple organ failure, and the APACHE II scores." (PMID 24826895, 2014).
Mycobacterium avium infection (1 paper, 2020). "In an in vivo mouse model of Mycobacterium avium infection, chronic infection triggers IFNγ-mediated proliferation of both LT-HSCs (CD34−Flk2− LSK or CD150+LSK) and ST-HSCs (CD34+Flk2−LSK)." (PMID 32373117, 2020).
myelolipoma (1 paper, 2024). "The expression of CD34, a stem cell marker, was downregulated in the myelolipoma and normal fat compared to adrenal tissues, indicating the presence of mature fat or terminally differentiated adipocytes in the myelolipoma." (PMID 38473790, 2024).
myositis (1 paper, 2017). "The characteristic immunostaining patterns of NF are positivity for α-SMA and myositis-specific autoantibodies and negativity for β-catenin, CD34, and cytokeratin." (PMID 28253912, 2017).
Nephrogenic systemic fibrosis (1 paper, 2008). "Nephrogenic systemic fibrosis (NSF) is a fibrosing disorder that exhibits CD34 expression in the majority of lesional spindle cells." (PMID 18799006, 2008).
nephrotic syndrome (1 paper, 2010). A collection of symptoms that include severe edema, proteinuria, and hypoalbuminemia; it is indicative of renal dysfunction. "The last strategy consisted in developing a humanized model of nephrotic syndrome through engraftment of CD34 + cells from nephrotic patients in NOD/SCID mice." (PMID 20649959, 2010).